FGF7 (fibroblast growth factor 7)
Diseases named in the same sentence as FGF7 in open-access papers (continued):
Sharing a sentence is not in itself a finding about the gene and the disease.
cholestasis (1 paper, 2018). Impairment of the bile flow caused by obstruction within the liver, or outside the liver in the bile duct system. "FGF7 is a fibroblast growth factor that has been shown to attenuate liver markers of cholestasis when overexpressed in the DDC mouse model." (PMID 30109019, 2018).
Cirrhosis (1 paper, 2012). A chronic disorder of the liver in which liver tissue becomes scarred and is partially replaced by regenerative nodules and fibrotic tissue resulting in loss of liver function. "BMP2, BMPR1A, FGF7, FGFR2 and ID3 were more highly expressed in cirrhosis than HCC, while the BMP inhibitors were more highly expressed in tumors." (PMID 23667740, 2012). "FGF7 and FGFR2, however, were over-expressed in both cirrhosis and HCC." (PMID 23667740, 2012).
Constipation (1 paper, 2023). Infrequent or difficult evacuation of feces. "We showed that FGF7 in human plasma is positively associated with constipation." (PMID 37501926, 2023).
craniosynostosis (1 paper, 2011). Craniosynostosis is defined as the premature fusion of one or more cranial sutures leading to secondary distortion of skull shape resulting in skull deformities with a variable presentation. "After controlling for variables contributing to potential bias, FGF7, SFRP4, and VCAM1 emerged as genes associated with single-suture craniosynostosis due to their significantly large changes in gene expression compared to the control population." (PMID 22028906, 2011). "Initially, the identification of FGF7 was most striking, since gain of function mutations in FGF-receptors (FGFRs) cause a number of craniosynostosis syndromes, including Apert, Crouzon, Muenke, and Pfeiffer syndromes." (PMID 22028906, 2011). "The results from this study not only identified FGF7, SFRP4, and VCAM1 as novel genetic candidates for the cause of single-suture craniosynostosis like, but also confirmed the involvement of ECM-mediated focal adhesion and Ffg/Wnt/Igf signaling pathways that may contribute its pathogenesis." (PMID 22028906, 2011). "Therefore, upregulation of signaling factors like FGF7 during mesenchymal condensation may lead to inappropriate ligand-receptor binding, increased mitogenic activity, and thus contribute to skeletal abnormalities related to craniosynostosis." (PMID 22028906, 2011).
dermatitis (1 paper, 2025). An inflammatory process affecting the skin. "FGF7 in the plasma increased with the development of dermatitis and ankylosing enthesitis." (PMID 39919800, 2025). "Thus, the expression of FGF7 at enthesis might also be up-regulated not only by skin inflammation, but also by trauma in human PsA." (PMID 39919800, 2025). "Plasma FGF7 concentration was determined at 6, 18, 20, and 28 wk of age in male DBA/1J mice caged together; the points correspond to the young, subclinical, initial, and advanced stage of the observed dermatitis and arthropathy, respectively." (PMID 39919800, 2025). "Collectively, our results indicated that the development of dermatitis in this PsA model was independent of FGF7 signaling." (PMID 39919800, 2025). "In addition, FGF7 expression in the skin did not change in dermatitis, indicating constitutive FGF7 expression." (PMID 39919800, 2025).
diabetic foot ulcers (1 paper, 2021). "FGF1, FGF2, FGF4, FGF7, FGF16, FGF21, and FGF23 have been found to have good therapeutic outcomes for diabetic foot ulcers." (PMID 34831463, 2021).
endometriosis (1 paper, 2025). The growth of functional endometrial tissue in anatomic sites outside the uterine body. "The findings demonstrated that FGF-7, FGF-10, and HGF exhibited significantly higher expression levels in the epithelium and stroma of normal controls compared to endometriosis samples." (PMID 40076699, 2025). "The immunohistochemical analysis focused on the expression of IFN-τ, FGF-7, FGF-10, FGF-23, and HGF in both normal endometrial tissues and deep endometriosis samples." (PMID 40076699, 2025).
enthesitis (1 paper, 2025). Inflammation at the site of insertion of ligaments, tendons, and other fibrous structures into bone. "The present study provides evidence of the role of FGF7 in the development of ankylosing enthesitis." (PMID 39919800, 2025). "The expression of FGF7 was up-regulated in the joints with the development of enthesitis." (PMID 39919800, 2025). "Collectively, our findings indicate that augmented IL-17A in PsA dermatitis induces the elevation of FGF7 levels in joint enthesis and results in a non-redundant role of FGF7 signaling in the development of ankylosing enthesitis in PsA." (PMID 39919800, 2025).
Follicular Cyst (1 paper, 2023). Cyst due to the occlusion of the duct of a follicle or small gland. "Although there are obvious differences between follicular cysts and tumors, we speculate that high levels of FGF7 and FGF10 expression may participate in the formation of follicular cysts in sows through activation of the MAPK signaling pathway." (PMID 38274662, 2023). "The transcriptomic analysis and prediction of upstream regulators in this study showed that FGF7 and FGF10 mRNA was significantly up-regulated in TIMG cells from follicular cysts compared with normal mature follicles." (PMID 38274662, 2023). "FGF7 regulated the PPAR signaling pathway (FABP5 and SCD) and the MAPK signaling pathway (FGF1, FGFR2, IL1A, TGFB1, and CSF1) and pathways in cancer (IL7, CD44, SMAD2, and MMP2) may be involved in the formation of follicular cysts." (PMID 38274662, 2023).
glaucoma (1 paper, 2024). Increased pressure in the eyeball due to obstruction of the outflow of aqueous humor. "Also, miR-200a could play a protective role in the glaucoma-induced optical nerve injury by inhibiting the FGF7-mediated MAPK signaling pathway." (PMID 38469119, 2024).
Hallux valgus (1 paper, 2021). Lateral deviation of the great toe (i.e., in the direction of the little toe). "Then we examined the mRNA levels of FGF family, FGF1, FGF4, FGF7, FGF8, FGF9 and found the high mRNA level of FGF9 in hallux valgus patients." (PMID 33456347, 2021).
hemangiopericytoma (1 paper, 2024). An antiquated term that refers to benign or malignant mesenchymal neoplasms characterized by the presence of neoplastic spindle-shaped to round cells arranged around thin-walled branching vascular spaces. "However, in a study of hemangiopericytomas and various control cell lines, fibroblast growth factor 7 (FGF7) and sFRP-4 were widely expressed in all studied cell lines and tissues and were not tumour-specific." (PMID 38731904, 2024).
hemorrhagic cystitis (1 paper, 2022). Inflammation of the bladder resulting in bloody urine. "In addition, several disease‐causing mutations/variants in the FGF7/10/FGFR2IIIb family have been described and as such, these individuals could be at heightened risk for life‐threatening hemorrhagic cystitis or urothelial cancer risk later in life if exposed to cyclophosphamide." (PMID 35854647, 2022).
Hirschsprung disease (1 paper, 2013). Hirschsprung disease (HSCR) is a congenital intestinal motility disorder that is characterized by signs of intestinal obstruction due to the presence of an aganglionic segment of variable extent in the terminal part of the colon. "A role for FGF7 for the migration of enteric neuroblasts has been suggested from analyses of CAMs and FGFs expression in Hirschsprung Disease patients." (PMID 24427155, 2013).
idiopathic pneumonia syndrome (1 paper, 2014). "FGF7, also known as KGF, has been shown to be effective in preclinical models of lung injury including acute lung injury and post-BMT-induced idiopathic pneumonia syndrome when given as a pretreatment." (PMID 25272285, 2014).
immune deficiency (1 paper, 2023). "FGF-7 also plays a role in the protection of TECs from cytotoxic therapy-induced damage as well as post-BMT immune deficiency caused by the loss of TECs." (PMID 37888466, 2023).
intestinal tumor (1 paper, 2025). "Related studies have demonstrated that GLP-1R activation upregulates in situ expression of fibroblast growth factor-7 (FGF7) in intestinal tumor cells, promoting tumor progression and inducing intestinal hyperplasia." (PMID 40140925, 2025).
invasive ductal carcinomas (1 paper, 2023). "used immunohistochemistry to demonstrate FGF7 expression in stroma of lobular carcinomas and invasive ductal carcinomas, and illustrated with Matrigel-embedded organoids that FGF7 increases cell proliferation." (PMID 37496657, 2023).
joint diseases (1 paper, 2025). "We demonstrated that IL-17A acts as an upstream mediator of FGF7 and that FGF7 plays an essential role in co-occurrence of cutaneous and joint diseases in PsA." (PMID 39919800, 2025).
meningioma (1 paper, 2012). A generally slow growing tumor attached to the dura mater. "We found that several growth factors including EGFL6, IGF1, FGF2, FGF7, FGF9, and FGF11 were overexpressed in fibroblastic meningioma, especially EGFL6 gene with extremely high expression in benign meningioma tissues." (PMID 23285163, 2012). "Expression of FGF2, FGF7, FGF9, and FGF11 was significantly increased 3.19-, 48.32-, 27.15-, and 3.34-fold respectively in fibroblastic meningiomas compared with arachnoidal tissue by qRT-PCR." (PMID 23285163, 2012).
myocardial infarction (1 paper, 2025). Gross necrosis of the myocardium, as a result of interruption of the blood supply to the area, as in coronary thrombosis. "FGF7 overexpression alleviated myocardial infarction in mice." (PMID 40362725, 2025).
myopia (1 paper, 2025). "Associated with FGF10, FGF7 has been confirmed to regulate specific mesenchymal-epithelial transition pathologically associated with extreme high myopia, validating our prediction." (PMID 40110040, 2025).
Nephroblastoma (1 paper, 2013). An embryonal neoplasm characterized by the presence of epithelial, mesenchymal, and blastema components. "Acidic fibroblast growth factor, FGF1 (−2.96) and FGF7 (−1.473) were also down-regulated, as well as NOV-like CTGF- member of the CCN protein family: nephroblastoma overexpressed/NOV (−3.149)." (PMID 24344983, 2013).
nephrolithiasis (1 paper, 2024). The presence of a calculus in the pelvis of the kidney; this is most often composed of mineral salts and proteins. "Injecting mouse models of nephrolithiasis with FGF7 resulted in urothelium proliferation and enhanced retention of calcium stones in the kidneys." (PMID 39680213, 2024). "Interestingly, FGF7 can bind to both domain III and domain V, where mutation in the latter has previously been reported to cause early-onset nephrolithiasis in patients with SJS." (PMID 39680213, 2024).
neurofibromatosis type 1 (1 paper, 2018). A clinically heterogeneous, neurocutaneous genetic disorder characterized by cafe-au-lait spots, iris Lisch nodules, axillary and inguinal freckling, and multiple neurofibromas. "Dermal factors have also been identified to be abnormally expressed in pigmentary lesions, such as KGF/FGF7, HGF and SCF in lentigo senilis and an increased secretion of SCF and HGF by dermal fibroblasts in neurofibromatosis type 1 (NF-1) disease." (PMID 30205563, 2018).
oral cavity cancer (1 paper, 2021). A primary or metastatic malignant neoplasm involving the oral cavity. "At 15q21.2, rs10851478 showed a significant risk effect to develop HPV(−) oral cavity cancers and also tend to be a cis-eQTL for the FGF7 gene specific of fibroblasts." (PMID 34642315, 2021).
pancreatic ductal adenocarcinoma (1 paper, 2012). An infiltrating adenocarcinoma that arises from the epithelial cells of the pancreas. "Keratinocyte growth factor (KGF), also known as fibroblast growth factor-7, and KGF receptor (KGFR) play important roles in the growth of epithelial cells and are overexpressed in a variety of malignant epithelial tumors, including pancreatic ductal adenocarcinoma (PDAC)." (PMID 22159401, 2012).
parasitic infection (1 paper, 2023). "Production of all molecules except FGF-2 and FGF-7 was significantly reduced in the CSF of EAE mice with parasitic infection." (PMID 36836678, 2023).
Parkinson disease (1 paper, 2021). A progressive degenerative disorder of the central nervous system characterized by loss of dopamine producing neurons in the substantia nigra and the presence of Lewy bodies in the substantia nigra and locus coeruleus. "Insignificant increase in HGF and a marked increase in FGF-7 expression were also observed in our study, suggesting that E. umbellata extracts could potentially be used in the treatment of disorders with neuro-inflammation, such as Alzheimer’s or Parkinson’s diseases." (PMID 33552740, 2021).
periodontitis (1 paper, 2016). An acute or chronic inflammatory process that affects the tissues that surround and support the teeth. "The HW group exhibited significantly upregulated expression of FGF7 mRNA as compared to that in the periodontitis group at both 3 and 7 days after treatment (p < 0.05; p < 0.01)." (PMID 26798423, 2016).
prostatic hyperplasia (1 paper, 2023). "In prostatic hyperplasia fibroblasts expressing AR, fibroblast growth factor-2 (FGF-2) and fibroblast growth factor-7 (FGF-7) were overexpressed." (PMID 36902608, 2023).
psoriatic arthritis (1 paper, 2025). Joint inflammation associated with psoriasis. "The authors indicated that IL-17A, which is produced in the skin, induces joint manifestations via FGF7 signaling in the pathology of psoriatic arthritis." (PMID 39919800, 2025).
renal carcinoma (1 paper, 2024). A carcinoma arising from the epithelium of the renal parenchyma or the renal pelvis. "To examine whether CAF-derived FGF7 contributes to ccRCC development, we first transformed NIH/3T3 into CAFs by coculturing them with RENCA renal cancer cells." (PMID 39594574, 2024).
tendinopathy (1 paper, 2025). "Single-cell RNA sequencing reveals an enrichment of a pro-fibrotic cell subpopulation in Fgf7-deficient tendons, which is also predominant in human tendinopathy." (PMID 41455730, 2025). "These suggest that FGF7 has potential as a pharmaceutical candidate for the treatment of tendon disorders, hinting at its translational application prospects." (PMID 41455730, 2025).
thymoma (1 paper, 2021). A neoplasm arising from the epithelial cells of the thymus. "Several important genes associated with thymus development, such as CLDN4, FGF7 and FGF10, showed high expression in certain thymoma subtypes and TCs, suggesting their potential role in the development of TETs." (PMID 34568003, 2021).
urothelial carcinoma (1 paper, 2020). A malignant neoplasm derived from the transitional epithelium of the urinary tract (urinary bladder, ureter, urethra, or renal pelvis). "In urothelial carcinoma of the upper urinary tract and bladder, FGF7 overexpression is an independent prognosticator." (PMID 33193571, 2020).
vitiligo (1 paper, 2017). Generalized well circumscribed patches of leukoderma that are generally distributed over symmetric body locations and is due to autoimmune destruction of melanocytes. "A recent work reported a decreased expression of KGF/FGF7 and its receptor in pathological hypopigmented skin, which may contribute to the formation of the classical milky macules of vitiligo." (PMID 29163360, 2017).
tumor (115 papers, 2005 to 2025). "It is possible that our observation of lower expression of FGF7 in ascites compared to tumor cells is due to reduced percentages of cancer-associated fibroblasts in the ascites specimens in comparison to the adherent tumor." (PMID 39886662, 2024). "In this study, we computationally and experimentally identified CAF-derived FGF7 as a causal factor driving ccRCC tumor growth via at least activating the PI-3K/AKT signaling pathway." (PMID 39594574, 2024). "In breast cancer patients, FGF7 was overexpressed and showed a significant association with tumor cell proliferation, angiogenesis, and epithelial-to-mesenchymal transition in mammary cells." (PMID 39766329, 2024). "FGF7 (keratinocyte growth factor KGF) was identified in tumours associated with TIO, and FGF7 and FGF23 were increased in blood draining the tumour site of a patient with TIO." (PMID 38731904, 2024). "Given that FGF7 functions as a secreted protein, we aimed to investigate its interaction with tumor cells through its association with specific receptors." (PMID 38491511, 2024). "To inspect the clinical implications of cell communications between CAFs, macrophages, endothelial cells, and tumour cells, we detected expression associations between signature genes (FGF7/THBS1/MS4A4A/ZEB1) and tumour miRNAs." (PMID 38778448, 2024). "In fact, the regulation of NFE2L2, and PTK2 expression are linked indirectly through FGF7, a member of the fibroblast growth factor family involved in wound repair and tumor development." (PMID 27812189, 2016). "Importantly, most canonical CAF‐associated genes and FGF7 in myoFib‐1 subset showed higher expression levels in tumour samples than in normal tissues." (PMID 38778448, 2024). "FGF7 is a potent epithelial cell-specific growth factor with an important role in morphogenesis of epithelium suggesting this variant as one of the malignancy-contributing factors from tumor stroma." (PMID 34642315, 2021). "Evidence from the clustering consensus analysis, single-cell analysis, and the experimental results illustrate that CAF-derived FGF7 plays a crucial role as a signaling mediator between CAFs and ccRCC tumor cells." (PMID 39594574, 2024). "We focused on the functions of MUC1 and FGF7 in cell communication since they showed a remarkably high expression in tumour cells and CAFs, respectively." (PMID 38778448, 2024). "As expected, FGF7 was significantly up-regulated in CAFs-CM, surpassing its expression levels in tumor cells and normal fibroblasts by several-fold." (PMID 38491511, 2024). "In summary, these findings suggest that FGF7 derived from CAFs facilitates in vivo tumor growth and EMT." (PMID 38491511, 2024). "Overall, this study delineates a key signaling axis governing the crosstalk between CAFs and ccRCC tumor cells, highlighting FGF7 as a promising therapeutic target of ccRCC." (PMID 39594574, 2024). "Consistently, our study revealed that FGF7 in the medium was more present in CAFs and less secreted in tumor cells." (PMID 38491511, 2024). "Reciprocally, tumor cells induced STAT3 signaling to up-regulate FGF7 expression at the transcript level in CAFs." (PMID 39594574, 2024). "They reported that thrombospondin 1 (which facilitates angiogenesis, tumor growth, and metastasis at the tumor site) expression was upregulated via FGF7-FGFR2b interaction through PI3K/Akt/mTOR signaling." (PMID 39766329, 2024). "The in vitro experimental evidence suggested that CAF-derived FGF7 can promote the cell growth and cell invasion of ccRCC tumor cells, which are mitigated by a specific inhibitor of the PI-3K/AKT signaling pathway." (PMID 39594574, 2024).